VPS35 (VPS35 retromer complex component)
Diseases named in the same sentence as VPS35 in open-access papers (continued):
Sharing a sentence is not in itself a finding about the gene and the disease.
Parkinson disease (continued). "Additional evidence that VPS35 dysfunction predisposes to familial Parkinson's disease will come from identification of other mutations which segregate with Parkinson's disease in families, and the observation that VPS35 mutations occur in PD patients in other populations." (PMID 22154191, 2012). "Notably, several studies link VPS35 mutations and retromer to Parkinson disease." (PMID 36538041, 2023). "Moreover, patients with VPS35[D620N] associated Parkinson's might benefit from LRRK2 inhibitor treatment that have entered clinical trials in humans." (PMID 29743203, 2018). "Notably, a series of Parkinson’s disease (PD)-related genes linked to the endomembrane system, including VPS35, LRRK2, GBA, TMEM175 and VPS13C were also identified indicating that PD proteins may act along the MAPL pathway to regulate immune signalling and cell death." (PMID 41083601, 2025). "Monogenic forms of Parkinson’s disease (PD) include SNCA, LRRK2, VPS35, RAB32, and CHCHD2, which are associated with autosomal dominant PD, and PRKN, PINK1, and DJ-1, which are associated with autosomal recessive PD1–3." (PMID 39988587, 2025). "Both familial PD due to VPS35 and DNAJC13 mutations present with typical dopa-responsive parkinsonism due to the loss of dopaminergic neurons in the midbrain; however, aS-positive Lewy bodies only appear in the latter." (PMID 38886344, 2024). "VPS35 plays a key role in neurodegenerative processes in Alzheimer’s disease and Parkinson’s disease (PD)." (PMID 38409392, 2024). "Together, the data reveal distinct differences between WT, VKI, and Haplo mice within the nigrostriatal dopamine system consistent with a LRRK2-dependent gain-of-function in VPS35 p.D620N parkinsonism." (PMID 38110354, 2023). "Here, we have expanded urine BMP analysis to other Parkinson’s disease (PD) associated mutations and found them to be consistently elevated in carriers of LRRK2 G2019S and R1441G/C as well as VPS35 D620N mutations." (PMID 37015928, 2023). "A major protein degradation pathway, autophagy, is critical to regulating protein turnover in neurons and has been connected to Parkinson’s disease-related mutations including SNCA, LRRK2, VPS35, parkin, Pink1 and DJ-1." (PMID 36864664, 2023). "We define how these components are impacted by Parkinson's pathogenic mutations (LRRK2[R1441C] and VPS35[D620N]) and LRRK2 inhibitors." (PMID 33367571, 2021). "Considerable researches have demonstrated that VPS35 plays an important role in Parkinson’s disease." (PMID 34001111, 2021). "Examples are PICALM/CALM contributing to Alzheimer’s disease pathology, C9ORF72 implicated in ALS and FTD and several genes linked to Parkinson’s disease such as LRRK2, VPS35, SNCA, Synj1 and EndoA." (PMID 34988081, 2021). "Our data with a small number of neutrophils isolated from VPS35[D620N] Parkinson's patients demonstrates a modest ∼1.5-fold increase in pRab1 levels that are reduced with MLi-2." (PMID 33367571, 2021). "Among those, a highly specific clone detects pThr73 levels in human peripheral blood cells of (mutant) LRRK2 G2019S and VPS35-D620N carriers with Parkinson's disease." (PMID 32601174, 2020). "Rubinzstein and colleagues have reported an accumulation of ATG9a at the TGN during autophagy upon suppression of endogenous VPS35 followed by re‐expression of the Parkinson‐related mutant VPS35‐D620N." (PMID 29158324, 2018). "Available data suggest that Parkinson's patients with VPS35[D620N] develop the disease at a younger age than those with LRRK2 mutations." (PMID 29743203, 2018). "Mutations in six genes are known to cause Parkinson's disease (PD) (autosomal dominant: alpha-synuclein, LRRK2, VPS35 and autosomal recessive: Parkin, PINK1 and DJ1) and number of other genes are implicated." (PMID 27872751, 2016). "More recently additional quality control genes/mutations have been reported linked for Parkinsonism, including DNAJC6, DNAJC13, VPS35 and ATP6AP2." (PMID 25170892, 2014).
Parkinson disease (continued). "Additionally, multiple Parkinson’s disease-related genes, including VPS35 and LRRK2, also regulate MAPL-induced pyroptosis." (PMID 41083601, 2025). "One intriguing question is why VPS35 mutations (e.g., D620N) cause Parkinson’s disease (PARK17) rather than AD." (PMID 40931359, 2025). "We cultured skin fibroblasts and iPSC-derived dopaminergic neurons from the proband and from a second, unrelated Parkinson's disease patient with the p.D620N VPS35 mutation, and compared them with isogenic and non-isogenic control cells." (PMID 41164908, 2025). "Accumulating evidence has demonstrated that VPS35 plays a critical role in Parkinson’s disease." (PMID 37950040, 2024). "Moreover, studies have demonstrated that inflammation-induced oxidative stress can lead to VPS35 dysfunction, contributing to the pathogenesis of neurodegenerative diseases such as Parkinson’s disease." (PMID 37830626, 2023). "Together the data support a chronic synaptopathy model for latent neurodegeneration, providing phenotypes and candidate pathophysiological stresses that may drive eventual transition to late-stage parkinsonism in VPS35 PD." (PMID 34530877, 2021). "A missense mutation, VPS35 p.D620N has been linked to a familial form of parkinsonism that is clinically indistinguishable from idiopathic late-onset PD141,142." (PMID 33674612, 2021). "The connection of VPS35 with tau pathology in Parkinson’s disease models is intriguing, and VPS35 levels were shown to be reduced in vulnerable forebrain regions of subjects with different tauopathies, including Alzheimer’s disease, Pick’s disease and progressive supranuclear palsy." (PMID 34704029, 2021). "A key caveat to our understanding of how VPS35 mutations link to Parkinson’s is that, to date, no VPS35 mutation brains have come to post-mortem pathological analysis, and therefore it is not known if VPS35 PD is a synucleinopathy." (PMID 31969802, 2019). "In Parkinson's disease, mutations of LE/lysosome proteins and motor complexes, such as LRRK2, Vps35, DCTN1, have been previously documented, suggesting that LE sorting defect and axonal transport disruption could play a causal role in this pathology." (PMID 26685126, 2016). "In conclusion, further study of VKI mice may elucidate the ontology of VPS35 p.D620N parkinsonism." (PMID 30155515, 2018). "With this background, we screened 150 familial PD cases from our UK familial Parkinson's Disease series, in which we have previously identified LRRK2, VPS35 and SNCA mutations in order to determine whether we could provide further that this gene is indeed a PD-related locus." (PMID 22561553, 2012). "Proteins known to be involved in Alzheimer’s disease progression, (such as CLU, APOE, and ADAM10) and Parkinson’s Disease (such as PARK7 and VPS35) were also identified, suggesting a potential role of GDE2-released EVs in neurodegeneration." (PMID 39272985, 2024). "The absolute number of people with Parkinson’s disease who tested positive for PINK1, PARK7, VPS35 and SNCA was extremely low, precluding any detailed comments about genotype-phenotypes or participant characteristics for these groups." (PMID 39074992, 2024). "The role of VPS35 was verified in multiple neurodegenerative diseases, including AD, ALS, and Parkinson’s disease (PD)." (PMID 39596030, 2024). "Well-established Parkinson’s disease genes include autosomal dominant forms (SNCA, LRRK2, and VPS35) and autosomal recessive forms (PRKN, PINK1 and DJ1)." (PMID 35328025, 2022). "By comparing the impact of neuronal deletion of VPS35 in mice to existing VPS35 mouse models, our data support the concept that Parkinson’s disease-linked VPS35 mutations do not manifest a complete loss-of-function effect and instead may operate in a more subtle manner to alter retromer function." (PMID 34704029, 2021).
Parkinson disease (continued). "Research has also shown that disruption of retromer function either by ablation of Parkinsonism related PLA2G6 and VPS35, or by overexpression of alpha-synuclein, leads to ceramide accumulation, lysosomal and mitochondrial stress, and neurodegeneration." (PMID 34514546, 2021). "However, mutations in several genes have been shown to result in clinically typical autosomal dominant (SNCA, LRRK2, VPS35, DNAJC13) or recessive (PARK2, PINK1, PARK7) PD, or parkinsonism with atypical features (e.g. PARK9)." (PMID 26399558, 2015). "Direct interactions between genetic components and these pathways are emerging, whether VPS35 and RME-8 in late onset PD, or parkin and PINK1 in mitophagy in early onset parkinsonism." (PMID 25061481, 2014). "At least 19 genetic loci for Parkinsonism have been identified to date, ten of which are autosomal dominant genes: SNCA (PARK1/PARK4), PARK3, UCHL1 (PARK5), LRRK2 (PARK8), GIGYF2 (PARK11), HTRA2 (PARK13), VPS35 (PARK17), EIF4G1 (PARK18), TMEM230 (PARK21), and CHCHD2 (PARK22)." (PMID 34356877, 2021). "Moreover, ARPC1B-deficient patients do not exhibit symptoms of spastic paraplegia or Parkinson’s disease, due to mutation in the strumpellin subunit of the WASH complex and mutation in the VPS35 subunit of the retromer complex, respectively." (PMID 31710310, 2019). "These hub genes, particularly VPS35, VPS29, and GAK, hold potential not only as molecular drivers of Parkinson’s disease but also as candidates for developing non-invasive urinary biomarkers for early diagnosis and therapeutic targeting." (PMID 40130009, 2025).
Parkinsonism (31 papers, 2014 to 2024). Characteristic neurologic anomaly resulting from degeneration of dopamine-generating cells in the substantia nigra, a region of the midbrain, characterized clinically by shaking, rigidity, slowness of movement and difficulty with walking and gait. "Several other vacuolar protein sorting receptors, such as VPS35, DNAJC26 (GAK) and DNAJC13 (RME-8) are also implicated in monogenic parkinsonism or PD risk." (PMID 38559229, 2024). "Mutations in seven genes were robustly associated with autosomal dominant (SNCA, LRRK2, EIF4G1, VPS35) or recessive (parkin/PARK2, PINK1, DJ1/PARK7) PD or parkinsonism." (PMID 29881367, 2018).
Alzheimer disease (30 papers, 2009 to 2026). A progressive, neurodegenerative disease characterized by loss of function and death of nerve cells in several areas of the brain leading to loss of cognitive function such as memory and language. "While reduced retromer levels have long been shown in Alzheimer’s disease brains, and VPS35 mutations linked with familial Parkinson’s disease, a connection between ALS and the retromer has only recently emerged." (PMID 34704029, 2021). "Dysfunctional Vps35 is a risk factor for neurodegenerative diseases, including Parkinson’s and Alzheimer’s diseases." (PMID 31907392, 2020). "Dysfunctional VPS35 increases a risk for neurodegenerative diseases, including Alzheimer’s disease (AD) and Parkinson’s disease (PD)." (PMID 31771656, 2019). "Dysfunction of Vps35/retromer is believed to be a risk factor for neuro-degenerative disorders, including Parkinson’s disease (PD) and Alzheimer’s disease (AD) for the following reasons." (PMID 28934248, 2017). "Interestingly, expressing a mutant VPS35 associated with Alzheimer’s disease (L625P) rescues the effect of VPS35 knockdown on LTP, whereas expression of the PD-associated mutant (D620N) does not, demonstrating that the PD-associated mutant contributes to defects in LTP." (PMID 33737866, 2021). "Interestingly, both VPS35 and Parkin mutations are also associated with Alzheimer’s Disease (AD)." (PMID 28399880, 2017). "It is notable that VPS35 haploinsufficiency has been reported to enhance neuropathology in a mouse model of Alzheimer's disease, where amyloid plaques and neurofibrillary tangles highlight decreased autophagy as a prominent mechanism for this disease." (PMID 26251041, 2015). "While the homozygous deletion of VPS35 in mice results in early embryonic lethality, VPS35 haploinsufficiency has been reported to enhance Alzheimer's disease (AD)-like neuropathology in a mouse model of AD." (PMID 24740878, 2014). "Depletion in humans of other, related, retromer subunits, Vps26 and Vps35, which require either SNX1 or SNX2 in order to associate with endosomes, increases amyloid-β peptide production associated with Alzheimer's disease." (PMID 19309515, 2009). "Moreover, APLP2 was the most significantly enriched protein in the cerebrospinal fluid (CSF) of neuronal Vps35 KO mice, and in human Alzheimer’s disease patients." (PMID 37248224, 2023). "Furthermore, in a mouse model of Alzheimer’s disease, VPS35 heterozygosity worsens Alzheimer’s disease-like Aβ pathology by modulating BACE1 activity." (PMID 34704029, 2021). "VPS35 can regulate APP metabolism and Aβ formation, and its levels are reduced in Alzheimer’s disease (AD) brains." (PMID 31964406, 2020). "With regard to Alzheimer’s disease (AD), the first evidence came from protein profiling studies showing a reduction of VPS26 and VPS35 in brain regions affected by the disease." (PMID 30405388, 2018). "Importantly, we detected 25 HLA epitopes derived from 15 genes associated with Alzheimer’s and related dementias such as Tau, PLD3 (Alzheimer’s disease), TDP-43, FUS (Frontotemporal dementia), and PARK7, VPS35 (Lewy Body dementia)." (PMID 40568088, 2025).
breast carcinoma (10 papers, 2014 to 2026). "VPS35 has been reported to be significantly associated with the progression and prognosis of several tumours, like breast cancer, and liver cancer." (PMID 37950040, 2024). "We also clarified that vacuolar protein sorting-associated protein 35 (VPS35), one of ARGs in the risk model, was upregulated in breast cancer samples and cell lines." (PMID 34001111, 2021). "It is our novel finding that VPS35, as an autophagy-related encoding gene, is upregulated in breast cancer and positively associated with lymph node metastasis and ER negative." (PMID 34001111, 2021). "Among these 6 ARGs, VPS35 was a high-risk factor with prognostic value in breast cancer patients." (PMID 34001111, 2021). "Among the six ARGs, VPS35 was a high-risk factor for prognosis of breast cancer." (PMID 34001111, 2021). "In breast cancer, VPS35 increases the proliferation and invasion abilities of cells and is essential for autophagy completion." (PMID 37950040, 2024). "In this study, the prognostic risk model consisting of six ARGs (VPS35, TRIM21, PRKAB2, RUFY4, MAP1LC3A and LARP1) in breast cancer were identified." (PMID 34001111, 2021). "In conclusion, we identified a novel autophagy-related prognostic risk model consisting of six encoding gene (VPS35, TRIM21, PRKAB2, RUFY4, MAP1LC3A and LARP1) in breast cancer." (PMID 34001111, 2021). "All these results indicated that VPS35 promotes the progression and aggression of breast cancer and VPS35 plays an essential role in the completion of autophagy process." (PMID 34001111, 2021). "To further elucidate the role of VPS35 in breast cancer development, we analyzed the relationship between VPS35 expression of 120 breast cancer clinical tissues by IHC and clinical pathological factors." (PMID 34001111, 2021). "Subsequently, we analyzed the possible molecular mechanism of VPS35 promoting breast cancer progression." (PMID 34001111, 2021). "The migration and invasion of breast cancer cells were remarkably decreased upon VPS35 knockdown in MDA-MB-231." (PMID 34001111, 2021). "Subsequently, we examined VPS35 expression level in a series of breast cancer cell lines, including MCF-7, ZR-75-1, MDA-MB-231, Hs578T, SK-BR-3, MDA-MB-453 and normal breast epithelia MCF‐10A by Western blot." (PMID 34001111, 2021). "Our findings elucidated that VPS35 knockdown induced the transition of the LC3BI to LC3BII in breast cancer cells and yellow LC3 puncta in autophagosomes increasing." (PMID 34001111, 2021). "CCK8, Colony formation assay, Transwell migration/invasion assays and autophagy flux assay were used to confirm biological function of VPS35 in breast cancer." (PMID 34001111, 2021). "VPS35 overexpression was correlated with more aggressive phenotype of breast cancer and indicated worse prognosis in both progression-free survival and overall survival analyses." (PMID 34001111, 2021). "VPS35 is a necessary element for autophagy completion and also promotes breast cancer cell proliferation, migration and invasion." (PMID 34001111, 2021). "Meanwhile, VPS35 knockdown inhibited breast cancer cell proliferation, migration and invasion, suggesting that VPS35 promoted the progression of breast cancer." (PMID 34001111, 2021). "Herein, we investigated VPS35 expression status in breast cancer specimens and firstly assessed the correlation of VPS35 with clinical pathological factors and survival prognosis in breast cancer." (PMID 34001111, 2021). "In our present study, we found that VPS35 was high level in breast cancer tissues compared with normal breast tissues." (PMID 34001111, 2021). "To evaluate the prognostic role of VPS35 expression in breast cancer, we conducted Kaplan–Meier survival analysis." (PMID 34001111, 2021). "Endogenous SORLA was found to localize largely to early endosomes (identified by EEA1 and Rab5 expression) and retrograde vesicles (VPS35) in MDA-MB-361 breast cancer cells." (PMID 31138794, 2019).